LEP (leptin)
Diseases named in the same sentence as LEP in open-access papers (continued):
Sharing a sentence is not in itself a finding about the gene and the disease.
Obesity (continued). "Similar to the other genes associated with monogenic forms of obesity, LRP2 is also involved in the regulation of the leptin-melanocortin pathway." (PMID 25158045, 2014). "In summary, findings from this small randomized trial support LCD and LFD dietary interventions as potentially attractive methods for obesity-related breast cancer prevention, particularly through favorable modification of leptin among premenopausal women." (PMID 24790820, 2014). "Ginsenoside Rb1 has the potential for use as an antiobesity therapeutic agent that functions by modulating obesity-induced inflammation and improving central leptin sensitivity in HF diet-induced obesity." (PMID 24675731, 2014). "Although initially considered as a potential anti-obesity drug, the development of leptin resistance in obesity has limited this perspective so far." (PMID 24498181, 2014). "Leptin has been found to positively correlate with obesity and is a well-known regulator of food intake and energy balance." (PMID 24944677, 2014). "While leptin monotherapy for treatment of obesity is plagued by acquired resistance in humans and animals, preclinical studies have shown that the combination of leptin and amylin reduced weight to a greater extent than amylin alone." (PMID 26237477, 2014). "Ubiquitous, neuron-specific or POMC neuron-specific deletion of PTP1B leads to decreased body weight and fat mass, increased energy expenditure, increased leptin sensitivity, improved glucose homeostasis, and resistance to high-fat diet-induced obesity." (PMID 25352831, 2014). "In this study, gene expression values of the obesity marker genes leptin, adiponectin, TNFα and PPARγ were measured in paired SAT and VAT samples of 50 obese patients." (PMID 24427296, 2014). "One of the best examples of the endocrine role of the stomach is seen in its production of the ghrelin, obestatin and leptin, hormones that are known to contribute to many chronic diseases asscociated with obesity." (PMID 24716593, 2014). "Several reports have shown increased TNF-α, IL-6, resistin and leptin expression in obesity, type 2 diabetes, cardiovascular disease and metabolic syndrome." (PMID 24481132, 2014). "Leptin and adiponectin are the two most well studied adipokines produced by adipose tissue in relation to obesity-related cancers, including breast, colon, hepatic, and endometrial cancer." (PMID 25115836, 2014). "The present findings corroborate previous studies that showed an impaired interaction between leptin and insulin and the mesolimbic reward circuitry in obesity." (PMID 25368558, 2014). "Further studies are needed to differentiate between the effects of obesity, leptin, and other physiological parameters in these mice." (PMID 24744883, 2014). "Since obesity is a risk factor for T2DM, the relationship between leptin and T2DM is being extensively studied." (PMID 24809394, 2014). "Many studies have demonstrated that leptin induces endothelium-dependent and independent vasorelaxation and that this effect is impaired in obesity." (PMID 25521118, 2014). "On the other hand, obesity is an increase in fat storage, affecting the circulating levels of estrogen, androgen, and leptin; therefore, responsiveness of the hypothalamus-pituitary axis is impaired and menarche is delayed." (PMID 25237321, 2014). "Leptin, the product of the obese gene, is an adipocyte-secreted protein hormone playing a key role in the progression of obesity and hepatic steatosis." (PMID 24838072, 2014). "We reasoned that leptin resistance, as seen in obesity and diabetes, would likely increase PS1 expression in the brain and, as a consequence, β-amyloid deposition in the db/AD mice." (PMID 24916066, 2014). "Plasma adiponectin levels were less affected by dietary LNA, suggesting that leptin is a more sensitive marker of early obesity development." (PMID 24081493, 2014).
Obesity (continued). "Based on these findings, the use of exogenous leptin as an anti-obesity therapy was initially viewed as a promising therapeutic option, and was investigated in multiple clinical trials." (PMID 26237477, 2014). "Animal models characterized by reduced-leptin signaling show hyperphagia, obesity, and insulin resistance, and leptin management improves insulin sensitivity and glucose metabolism in these models." (PMID 25202741, 2014). "Adiponectin levels are lower in subjects with obesity and type 2 diabetes; leptin and c-reactive protein correlate positively with body mass index, insulin resistance and diabetes." (PMID 25208549, 2014). "Leptin, an anti-obesity adipocytokine, regulates body weight by modifying energy levels and increasing the metabolic rate while decreasing food intake." (PMID 24795698, 2014). "The development of resistance to leptin effects has been proposed to explain its reduced activity in obesity." (PMID 25105135, 2014). "We and others have demonstrated that human obesity can result from a multiplicity of defects in the leptin–melanocortin pathway." (PMID 25154910, 2014). "Among adenoma-free controls, there were similar differences in measures of obesity, adiponectin and leptin, fasting glucose, insulin, and smoking status between African Americans and Caucasians." (PMID 25197277, 2014). "This inconsistency is believed to result from leptin resistance that develops with high-fat feeding and obesity." (PMID 25165472, 2014). "In common obesity, there’s a phenomenon called leptin resistance reflecting the failure of leptin to inhibit energy intake and to increase energy expenditure." (PMID 25133088, 2014). "With obesity, serum leptin resistance increases due to the central hypothalamic action and lipocytokine mechanisms for negative feedback or defect transport through the blood–brain barrier." (PMID 24410812, 2014). "Given the public health and financial issues at stake, Phase 1 and 2 studies were conducted with unusual swiftness, showing that leptin was safe, but also that its effectiveness in curbing appetite and reducing obesity was variable and less than stellar." (PMID 25177314, 2014). "Recent studies have suggested that leptin is also involved in the pathogenesis of obesity-related atherosclerosis and cardiovascular disease." (PMID 24410779, 2014). "Obesity is related to an increase in the number and size of adipocytes, which results in changes in adipokines synthesis, including leptin." (PMID 24825928, 2014). "Earlier reports showed circulating leptin concentrations to be elevated in obese subjects in proportion to the degree of adiposity and positively correlated with body fat mass, despite anti-obesity actions of leptin." (PMID 25276234, 2014). "Correlation between leptin and resistin and the inflammatory markers was found to be highly dependent on obesity, in contrast to the one between adiponectin and TNF-α." (PMID 24736687, 2014). "Since the discovery of leptin in 1994, most studies have described the role of leptin in the regulation of a series of endocrine systems and in obesity." (PMID 24502529, 2014). "Obesity and the associated metabolic syndrome are complex phenotypes characterized by diabetes, hyperglycemia, insulin resistance, fatty infiltration of the liver and acquired leptin resistance, all of which might influence the course of viral infection through overlapping or independent mechanisms." (PMID 25232724, 2014). "We have previously shown that insulin signaling is one of the factors responsible for the development of obesity related hypertension which is later maintained by slowly rising circulating leptin concentrations." (PMID 25520669, 2014). "In the presence of leptin resistance, due to obesity, leptin is supposed to be unable to stimulate GnRH secretion, with consequent low levels of FSH and LH and hypogonadism." (PMID 25254043, 2014).
Obesity (continued). "A news report commenting on these findings discussed the acquisition of the license to develop leptin by the biotech company Amgen and the potential for turning the discovery into obesity drugs." (PMID 25177314, 2014). "Since the discovery of leptin in 1994, major advances have been made in understanding the neuroendocrine mechanisms regulating appetite, adiposity, obesity, metabolism, sympathetic tone, blood pressure, inflammation, and the hematopoietic and immune systems." (PMID 24868483, 2014). "In mammals, leptin is elevated in obesity, playing a role in the onset of chronic inflammation, being a modulator of T-cell activity." (PMID 25333488, 2014). "The positive effect of leptin inhibition on trabecular bone fraction and weight gain in diet-induced obesity resistant PRLR−/− mice, suggests that leptin and PRL signaling pathways are acting separately from each other." (PMID 24667351, 2014). "Leptin monotherapy, however, has not been successful in reducing food intake and weight gain in obese humans as originally hoped, possibly due to preexisting leptin resistance in obesity." (PMID 25412152, 2014). "Ginsenoside Rb1 has potential for use as an anti-obesity therapeutic agent that modulates obesity-induced inflammation and improves central leptin sensitivity in HF diet-induced obesity." (PMID 24675731, 2014). "Protein tyrosine phosphatase 1B (PTP1B) is a key negative regulator of insulin and leptin signaling, which suggests that it is an attractive therapeutic target in type II diabetes and obesity." (PMID 24865376, 2014). "In contrast, leptin and resistin correlated with the inflammatory markers, and this correlation was obesity-dependent." (PMID 24736687, 2014). "Accordingly, the interactions between leptin and inflammation are bidirectional: Pro-inflammatory cytokines increase the synthesis and release of leptin, which in turn contribute to maintain a chronic inflammatory state in obesity." (PMID 24733068, 2014). "A vast number of reports suggest that leptin is a legitimate key candidate linking obesity to carcinogenesis." (PMID 25019059, 2014). "Relatively mild and chronic inflammation related to diet-induced obesity has been shown to inhibit leptin signaling and thereby increasing food intake." (PMID 24911652, 2014). "As adiponectin and leptin are considered to have opposing effects on inflammation in obesity, these findings rather indicate a pro-inflammatory role of chemerin in NDO patients." (PMID 24702860, 2014). "Leptin is an enzyme that is secreted from white adipose tissue and its concentration depends on the degree of obesity, being higher in obese individuals." (PMID 24936481, 2014). "In obesity, there is also a defective transport of leptin across the BBB, which suggests the existence of central leptin resistance." (PMID 24795698, 2014). "Interest on the pathophysiology of obesity has been intensified recently with the discovery of leptin." (PMID 24495350, 2014). "In contrast to leptin, adiponectin levels decrease prior to the onset of obesity and insulin resistance and attenuate the degree of inflammation and insulin resistance." (PMID 25309775, 2014). "This study demonstrates that the hormone leptin negatively interferes with the regenerative capacity of PDL cells, suggesting leptin as a pathomechanistic link between obesity and compromised periodontal healing." (PMID 25136363, 2014). "Mice lacking SOCS3 in this particular population of neurons are protected from the development of diet-induced obesity and maintain central leptin sensitivity." (PMID 24600449, 2014). "The current model suggests that obesity in human is due to a desensitization to leptin while within gliomas, there is a correlation between tumor grade and tumor expression of leptin and its receptor." (PMID 25041817, 2014). "Taken together, the effects of elevated leptin in obesity can drive CRC tumor growth and progression." (PMID 25019059, 2014).
Obesity (continued). "It is reported that PTP1B knockout mice exhibit increased insulin and leptin sensitivity and are resistant to high-fat diet-induced obesity (DIO)." (PMID 24987707, 2014). "Since then, various studies have been carried out to elucidate the role of leptin in energy homeostasis particularly in the brain giving further insight into its role in obesity." (PMID 25147530, 2014). "Leptin, which is also known as adipose tissue peptide hormone, plays an important role in the regulation of body fat and, therefore, it is called the obesity hormone." (PMID 24051404, 2013). "Ghrelin is a physiological antagonist of leptin; it leads adiposity and obesity, so in obese patients ghrelin levels decrease as well." (PMID 24049662, 2013). "We previously reported that neuron-specific restoration of SH2B1β transgenes (Tg) into SH2B1 knockout (KO) mice (called TgKO mice) fully corrects leptin resistance, hyperphagia, and obesity in TgKO mice." (PMID 24358267, 2013). "In support of separate but coordinated action of serotonin and leptin, the obesity phenotype of leptin-overexpressing mice on a high-fat diet was exacerbated in the absence of 5HT2CR." (PMID 23543912, 2013). "We found that genetically lean females reared by obese mothers presented early postnatal hyperleptemia, selectively reduced response to leptin and sensitivity to diet induced obesity when exposed to a high palatable diet as adults." (PMID 23544111, 2013). "Plasma leptin has a strong correlation with obesity, T2DM, CVD, insulin resistance, metabolic syndromes, and inflammatory markers." (PMID 24282409, 2013). "When BDNF signaling is compromised, neural circuits in these hypothalamic areas are dysfunctional and fail to transmit the anorexigenic signal of leptin, leading to leptin resistance and obesity." (PMID 23519010, 2013). "Leptin resistance is a common feature seen in obese patients that has limited the use of leptin for the treatment of obesity." (PMID 23527232, 2013). "SOCS3 overexpression in the hypothalamus induces leptin resistance and obesity, while its inactivation in the hypothalamus has been shown to enhance the response to endogenous satiety signals and attenuate obesity in mice fed a high-fat diet." (PMID 23967267, 2013). "In leptin-deficient ob/ob mice, loss of either Promch or MCH-containing neurons improved obesity, diabetes, and hepatic steatosis, suggesting that MCH is an important mediator of the response to leptin deficiency." (PMID 23626585, 2013). "In summary, obesity in mice is associated with upregulated expression of ANXA1 in adipose tissue and this occurs in a leptin- and IL-6-independent fashion." (PMID 24312665, 2013). "SH2B1 directly enhances leptin signaling in cultured cells; therefore, neuronal SH2B1 exerts anti-obesity action at least in part by enhancing leptin sensitivity." (PMID 24358267, 2013). "Leptin administered either systemically or centrally increases sympathetic nerve activity to at least some target tissues, and, with chronic administration sufficient to mimic leptin levels seen in obesity, can lead to increases in arterial pressure." (PMID 23408476, 2013). "PTP1B is a negative regulator of the leptin and insulin signaling pathways, so it has emerged as an attractive novel target for the treatment of both type 2 diabetes and obesity." (PMID 23092275, 2013). "Therefore, in this study, we sought to determine whether NAFLD development was due to both a disruption in hepatic mitochondrial content and function as well as an upregulation of hepatic de novo lipogenesis markers in the commonly studied model of obesity, the leptin-deficient Ob/Ob mouse." (PMID 23401753, 2013). "The present study was designed to examine the salubrious effects of resveratrol as a neuroprotective antioxidant on brain of ob/ob mice, a model of severe obesity with insulin resistance, resulting from defective leptin signaling." (PMID 24163719, 2013).
Obesity (continued). "Leptin deficiency in ob/ob mice and leptin receptor deficiency in db/db mice led to hyperinsulinemia even before the progression of obesity and diabetes and this hyperinsulinemia was ameliorated by administration of recombinant leptin to the ob/ob mice." (PMID 24032047, 2013). "Analysis of the gene expression profile of the four groups of ASCs revealed obesity induced alterations in several key genes, including leptin (LEP)." (PMID 24176089, 2013). "At the same time, the leptin is still produced but it cannot activate the leptin receptors and restrain obesity and hyperinsulinemia induced by NPY." (PMID 23671868, 2013). "The current review summarizes the recent knowledge regarding the malfunction of adipokines such as leptin, resistin, and visfatin in the initiation and progression of many metabolic diseases including obesity, diabetes and immunity." (PMID 23634778, 2013). "In sum, adult OdLp females were characterized by a normal phenotype, but showed a permanent disruption in estrous cycle parameters, decreased response to leptin and sensitivity to diet induced obesity when exposed to an unbalanced/palatable diet." (PMID 23544111, 2013). "Patients with obesity have higher leptin levels and are thought to manifest leptin resistance, in that the satiety inducing effect of leptin is reduced." (PMID 24250335, 2013). "It is important to point out that as metabolic pathways change with obesity (e.g., rising leptin levels), these changes can feedback to the SCN and lead to rhythm changes." (PMID 23550218, 2013). "Among these, regression analysis found four well-established obesity associated genes that were positively correlated (CPE, LEP, NPY1R, and NPY5R), and two genes (APOM, and CRP) that were negatively correlated with weight gain." (PMID 23544116, 2013). "Obesity is characterized by leptin resistance and increased leptin levels, and by reduced levels of circulating adiponectin." (PMID 24115945, 2013). "HFD-induced obesity in mice increases hyperleptinemia and hypothalamic leptin resistance through induction of suppressor of cytokine signaling (SOCS)-3." (PMID 23696840, 2013). "Leptin, whose serum concentration is increased in obesity and breast cancer, stimulates cell proliferation by up-regulating the expression of cdk2 and cyclinD1." (PMID 23750285, 2013). "Obesity activates many inflammatory pathways that deregulate physiological responses, which maintain metabolic homeostasis including insulin and leptin sensitivity." (PMID 23594407, 2013). "On the contrary, knock down of Atg7 in the mediobasal hypothalamus as well as in propriomelanocortin (POMC) neurons, favors the onset of an obesity phenotype and leptin resistance." (PMID 24376631, 2013). "Leptin, a 167-amino acid hormone and a biomarker of the obesity regulatory gene, is produced by fat tissue and is known to regulate energy intake and metabolism." (PMID 23990846, 2013). "Some of the adipokines hormones such as leptin, adiponectin, resistin, and ghrelin play a role in the regulation of glucose metabolism and are involved in the development of obesity, diabetes, inflammation, auto-immunity and metabolic syndromes." (PMID 23634778, 2013). "In cases of obesity with hyperleptinemia and central insensitivity for leptin, dominant is the beneficial peripheral effect, which consequently leads to higher bone mineral density among patients." (PMID 24319457, 2013). "In this regard, plasma leptin concentrations under conditions of severe obesity can exceed 100 ng/ml and it would therefore be of importance to determine cardiac FTO expression under more pronounced hyperleptinemic conditions." (PMID 24019958, 2013).